RTN4IP1 (reticulon 4 interacting protein 1)
Description:
NAD(P)H oxidoreductase involved in the ubiquinone biosynthetic pathway. Required for the O-methyltransferase activity of COQ3. Able to catalyze the oxidoreduction of 3-demethylubiquinone into 3-demethylubiquinol in vitro. However, it is unclear if 3-demethylubiquinone constitutes a substrate in vivo. May also play a role in the regulation of retinal ganglion cell (RGC) neurite outgrowth, and hence in the development of the inner retina and optic nerve (By similarity). Appears to be a potent inhibitor of regeneration following spinal cord injury (By similarity).
Synonyms: NIMP; Yim1; OPA10
Tractability: Small molecule: a structure with a bound ligand is known. PROTAC: ubiquitination databases record sites on it; its protein half-life has been measured.
Gene: Protein-coding gene on chromosome 6 (106,570,771 to 106,629,498, reverse strand). Ensembl gene ENSG00000130347.
Subcellular location: Mitochondrion matrix; Mitochondrion outer membrane
Gene Ontology:
Molecular function: NADH dehydrogenase (quinone) (non-electrogenic) activity; NADPH dehydrogenase (quinone) activity; protein binding; oxidoreductase activity; zinc ion binding
Biological process: ubiquinone biosynthetic process; regulation of dendrite development
Cellular component: mitochondrial matrix; mitochondrial outer membrane; mitochondrion
Genetic constraint (gnomAD): Loss-of-function variants: 29 observed, 41.52 expected, observed/expected ratio (o/e) 0.7, 90% interval 0.52 to 0.95. The upper end of that interval is the gene's LOEUF score, 0.95, which puts it in group 4 of 6, group 1 being the genes least tolerant of losing a copy. Missense variants: 392 observed, 471.41 expected, observed/expected ratio (o/e) 0.83, 90% interval 0.76 to 0.9. Synonymous variants: 155 observed, 157.61 expected, observed/expected ratio (o/e) 0.98, 90% interval 0.86 to 1.12.
Gene-disease validity (ClinGen):
ClinGen rates the evidence that RTN4IP1 causes each of these diseases.
optic atrophy 10 with or without ataxia, intellectual disability, and seizures (autosomal recessive): Definitive.
Homologues: Orthologues: chimpanzee RTN4IP1 (99% identical), macaque RTN4IP1 (97% identical), rabbit RTN4IP1 (94% identical), dog RTN4IP1 (92% identical), guinea pig RTN4IP1 (92% identical), mouse Rtn4ip1 (90% identical), pig RTN4IP1 (87% identical), rat Rtn4ip1 (85% identical), tropical clawed frog rtn4ip1 (65% identical), zebrafish rtn4ip1 (64% identical), Caenorhabditis elegans rad-8 (35% identical), Drosophila melanogaster CG17221 (34% identical). Paralogues in human: CRYZ (22% identical), TP53I3 (22% identical), MECR (21% identical), VAT1 (21% identical), VAT1L (21% identical), ADH4 (21% identical), ADH1A (20% identical), ADH1B (20% identical), ADH1C (20% identical), CRYZL1 (19% identical), ADH5 (19% identical), ADH7 (18% identical), and 5 more.
Diseases named in the same sentence as RTN4IP1 in open-access papers:
RTN4IP1 is named in the same sentence as 45 diseases in open-access papers, as found by Europe PMC text mining. Sharing a sentence is not in itself a finding about the gene and the disease. The quoted sentences say what the papers report.
optic atrophy (10 papers, 2020 to 2025). A disorder characterized by loss of optic nerve fibers. "Recessive mutations in RTN4IP1 have been identified through whole-exome sequencing in several patients exhibiting severe central nervous system diseases and optic atrophy." (PMID 40301572, 2025). "Optic atrophy, seizures, nystagmus, and global developmental delay are the most common symptoms associated with pathogenic variants in the RTN4IP1." (PMID 36231115, 2022). "In conclusion, we report a novel deleterious variant in RTN4IP1 leading to intellectual disability, encephalopathy, ataxia, optic atrophy, and seizures in our patients." (PMID 36231115, 2022). "This has been clearly contradicted by the SSBP1 gene example, where mtDNA depletion leads to defective bioenergetics, leading simultaneously to optic atrophy and retinal dystrophy, as well as the case of RTN4IP1 mutations and other rare conditions." (PMID 35008635, 2021). "Biallelic recessive variants in RTN4IP1 induce early onset optic atrophy with seizures and mild cognitive impairment." (PMID 33426505, 2020). "Interestingly, the only reported case of pathogenic human PYURF variants presented neonatally with profound metabolic acidosis and multisystem mitochondrial disease, which included optic atrophy, a similar clinical presentation to RTN4IP1 deficiency." (PMID 40859035, 2025). "Fundus changes in patients with variants in seven genes exhibited optic atrophy plus retinal degeneration in our in-house cohort, including ACO2, FDXR, NBAS, OPA3, RTN4IP1, SSBP1 and C12ORF65." (PMID 39423307, 2025). "The carriers of OPA3, RTN4IP1, FDXR and C12orf65 mutations in our cohort also manifested optical atrophy plus retinal degeneration." (PMID 39423307, 2025).
Optic neuropathy (6 papers, 2017 to 2026). "RTN4IP1 encodes a mitochondrial oxidoreductase essential for coenzyme Q biosynthesis; pathogenic variants have been reported mainly in optic neuropathy and encephalopathy." (PMID 41609474, 2026). "On the other hand, RTN4IP1 mutations are associated with recessive optic neuropathy and additional neurological symptoms in humans." (PMID 39757767, 2025). "According to human genetic studies, RTN4IP1 is associated with optic neuropathy, muscle loss and global developmental delay, indicating mitochondrial dysfunction." (PMID 37884807, 2024). "Bi-allelic variants in RTN4IP1, also known as Optic Atrophy-10 (OPA10), lead to early-onset recessive optic neuropathy, atrophy, and encephalopathy in the afflicted patients." (PMID 36231115, 2022). "A recent report found that mutations in RTN4IP1, the rad-8 ortholog, lead to inherited optic neuropathy." (PMID 28539870, 2017). "Our results further support the suggestion that RTN4IP1 abnormalities result in early-onset optic neuropathy and neurological features, including mild intellectual disability and epilepsy." (PMID 36231115, 2022).
Encephalopathy (4 papers, 2021 to 2026). Encephalopathy is a term that means brain disease, damage, or malfunction. "Mutations in the RTN4IP1 lead to OPA10, which is an autosomal recessive inherited condition that often presents with additional neurological symptoms, such as epilepsy, chorea, or encephalopathy." (PMID 39201313, 2024). "Patients generally present with syndromic autosomal OA, with epilepsy, chorea and encephalopathy commonly reported, and it is suggested that more severe symptoms are associated with more deleterious mutations in the RTN4IP1/OPA10 gene." (PMID 34867178, 2021).
breast carcinoma (3 papers, 2021 to 2025). "Further, we analyzed the correlations among RTN4IP1, c‐Myc, and IRP2, and assessed the expression patterns of these genes in thyroid and breast cancers." (PMID 39757767, 2025). "Other genes, such as RTN4IP1 and TBCC, have been reported to be related to breast cancer progression." (PMID 33663517, 2021). "We found that RTN4IP1 is regulated by different mechanisms in ESCC and breast cancer, and that the mechanism may be common for ESCC and thyroid cancer." (PMID 39757767, 2025). "These preliminary analyses suggest that the c‐Myc–IRP2 axis contributes to RTN4IP1 elevation, specifically in ESCC (and thyroid cancer), and other mechanisms may be responsible for RTN4IP upregulation in breast cancer, such as promoter methylation and gene amplification." (PMID 39757767, 2025).
Ataxia (2 papers, 2022 to 2024). Ataxia refers to impaired coordination of voluntary muscle movement. "Moreover, RTN4IP1 mutations may also result in extraocular manifestations appearing as mitochondrial encephalopathies, such as mild ataxia, intellectual disability, and rare generalized seizures." (PMID 36231115, 2022).
Retinal dystrophy (2 papers, 2021 to 2025). Retinal dystrophy is an abnormality of the retina associated with a hereditary process. "The predominant genes for retinal dystrophy are FDXR, SSBP1, ACO2 and RTN4IP1." (PMID 39423307, 2025).
deafness (1 paper, 2022). An inherited or acquired condition characterized by the complete loss of the ability to hear from one or both ears. "In addition, deafness, brain MRI abnormalities, stridor, and abnormal electroencephalograms were seen in severely affected patients with premature death due to the deleterious effect of the variants on RTN4IP1 activity and structure." (PMID 36231115, 2022).
muscle degeneration (1 paper, 2013). "Fewer (6 proteins; myosin-4, calsequestrin 1, ATP-citrate synthase, glycerol-3-phosphate dehydrogenase, fructose bisphosphate aldolase A, reticulon-4-interacting protein 1) were increased in control DIA and in the mdx EOM (which do not show muscle degeneration)." (PMID 23823696, 2013).
Nystagmus (1 paper, 2022). Rhythmic, involuntary oscillations of one or both eyes related to abnormality in fixation, conjugate gaze, or vestibular mechanisms. "Pathogenic RTN4IP1 variants cause numerous clinical features affecting the eyes, including reduced visual acuity, photophobia, and nystagmus." (PMID 36231115, 2022).
thyroid cancer (1 paper, 2025). "RTN4IP1 is a tumor suppressor in thyroid cancer; however, the underlying mechanism remains unknown." (PMID 39757767, 2025). "It was reported that RTN4IP1 is downregulated in thyroid cancer and exhibits tumor‐suppressive functions." (PMID 39757767, 2025). "Our findings shed light on the role of RTN4IP1 in thyroid cancer." (PMID 39757767, 2025).
cancer (5 papers, 2021 to 2026). A tumor composed of atypical neoplastic, often pleomorphic cells that invade other tissues. "To elucidate the role of RTN4IP1, we utilized a previously established methodology to analyze the Achilles dataset via the cancer dependency map portal (DepMap), aiming to identify genes that exhibit coessentiality with RTN4IP1." (PMID 40301572, 2025). "We further demonstrate that c‐Myc–IRP2–IRE axis is responsible for the upregulation of RTN4IP1, and identify SLC1A5, SLC3A2, and SLC7A5, three amino acid transporters implicated in cancer, as essential downstream effectors of RTN4IP1 in ESCC." (PMID 39757767, 2025). "The present study revealed that RTN4IP1 functions as a cancer‐promoting protein in ESCC by regulating amino acid transporters." (PMID 39757767, 2025). "Here, we present evidence of RTN4IP1 as a cancer‐promoting gene that is profoundly upregulated and essential for cell proliferation in ESCC." (PMID 39757767, 2025). "RTN4IP1 is a mitochondrial oxidoreductase, and its function in cancer remains obscure." (PMID 39757767, 2025). "RTN4IP1 is a putative mitochondrial oxidoreductase with unknown biological functions in cancer." (PMID 39757767, 2025). "Herein, we demonstrated that RTN4IP1 expression was substantially elevated in ESCC and defined the cancer‐promoting role of RTN4IP1 both in vitro and in vivo." (PMID 39757767, 2025). "Recent studies have revealed the emerging importance of RTN4IP1 in cancer; however, its role is not yet completely understood." (PMID 39757767, 2025). "Thus, RTN4IP1 emerges as a key cancer‐promoting protein in ESCC, suggesting therapeutic RTN4IP1 suppression as a promising strategy for ESCC treatment." (PMID 39757767, 2025). "Furthermore, fusion transcripts involving oncogenes have been shown to exhibit increased expression in cancer, and we observed indeed strong expression of CRYBG1, FGFR2, and RTN4IP1 in MFM-223." (PMID 38391914, 2024). "Finally, four novel enzymes with unappreciated biological functions in cancer were identified, namely thromboxane A synthase 1 (TBXAS1), 5′,3′‐nucleotidase, cytosolic (NT5C), glycosyltransferase 8 domain containing 2 (GLT8D2) and reticulon 4 interacting protein 1 (RTN4IP1)." (PMID 39757767, 2025).
mitochondrial disease (2 papers, 2025). "A closer inspection of the clinical phenotypes associated with primary CoQ10 deficiency and patients with RTN4IP1-related mitochondrial disease—and other CI-driven pathologies—reveals significant overlap." (PMID 40859035, 2025). "Thus, our data reveal RTN4IP1 plays necessary and independent roles in both the terminal stages of CI assembly and in coenzyme Q metabolism, and that pathogenic RTN4IP1 variants impair both functions in patients with mitochondrial disease." (PMID 40859035, 2025). "Computational analysis identifies RTN4IP1 and ECHS1 as key OXPHOS genes linked to mitochondrial diseases in humans." (PMID 40301572, 2025). "A CRISPR/Cas9-based galactose screening identifies key mitochondrial genes involved in OXPHOS and oxidative metabolism, highlighting RTN4IP1 and ECHS1 as uncharacterized regulators with potential implications for mitochondrial diseases." (PMID 40301572, 2025).
tumor (2 papers, 2019 to 2025). "We also found that c‐Myc overexpression elevated SLC1A5/SLC3A2/SLC7A5 expression in RTN4IP1‐deficient cells, and promoted cell proliferation as well as tumor growth upon RTN4IP1 knockdown, demonstrating the essential role of SLC1A5/SLC3A2/SLC7A5 in RTN4IP1‐mediated cell proliferation." (PMID 39757767, 2025). "Our data showed that effective RTN4IP1 depletion in PDX tumors resulted in significant inhibition of tumor growth, along with a significant decrease of Ki67‐positive malignant cells in RTN4IP1‐knockdown tumors." (PMID 39757767, 2025). "Interestingly, RTN4IP1 deficiency impaired the expression of multiple amino acid transporters, resulting in amino acid starvation; thus, RTN4IP1 knockdown impaired cell proliferation and tumor growth in ESCC." (PMID 39757767, 2025). "As RTN4IP1 mRNA level was significantly increased in ESCC tumor samples, we speculated that RTN4IP1 might be upregulated at the transcriptional level." (PMID 39757767, 2025). "The upstream regulatory mechanisms of RTN4IP1 may be complex and vary with tumor type." (PMID 39757767, 2025).
endocrine disease (1 paper, 2026). "This is the first report linking RTN4IP1 mutations to endocrine failure and suggesting a therapeutic role for CoQ10 in mitochondrial-related endocrine disease." (PMID 41609474, 2026).
RTN4IP1 also shares sentences with these, for which no sentence is quoted: epilepsy (3 papers); Chorea (2); developmental delay (2); Atrophy (1); autosomal recessive optic atrophy (1); B-cell lymphoma (1); Behr syndrome (1); central nervous system diseases (1); cerebellar ataxia (1); Cognitive impairment (1); Costeff syndrome (1); diffuse large B-cell lymphoma (1); esophageal adenocarcinoma (1); esophageal cancer (1); head and neck squamous cell carcinoma (1); hypoparathyroidism (1); infarction (1); Intellectual disability (1); lung adenocarcinoma (1); metabolic acidosis (1); metastatic disease (1); Multiple sulfatase deficiency (1); neurological disease (1); Onset (1); pancreatitis (1); panhypopituitarism (1); renal dysplasia (1); retinal degeneration (1); Sensorineural deafness (1); spastic ataxia (1).
A further 1 disease shares a sentence with RTN4IP1 in 1 paper.